PKD1P1 (polycystin 1, transient receptor potential channel interacting pseudogene 1)
Synonyms: HG1; NPIP
Gene: Transcribed unprocessed pseudogene on chromosome 16 (16,310,341 to 16,334,190, forward strand). Ensembl gene ENSG00000244257.
Diseases named in the same sentence as PKD1P1 in open-access papers:
PKD1P1 is named in the same sentence as 7 diseases in open-access papers, as found by Europe PMC text mining. Sharing a sentence is not in itself a finding about the gene and the disease. The quoted sentences say what the papers report.
cancer (4 papers, 2021 to 2025). A tumor composed of atypical neoplastic, often pleomorphic cells that invade other tissues. "The results of high-throughput sequencing showed that TRP ion channel-related genes, such as TRPC7-AS1, TRPC4AP, PKD1P6, and PKD1P1, were highly expressed in cancer tissues than those in paracancerous tissues." (PMID 34512754, 2021). "We also found that the expression of TRP ion channel-related genes such as TRPC7-AS1, TRPC4AP, PKD1P6, and PKD1P1 in cancer tissues was higher than those in adjacent tissues." (PMID 34512754, 2021).
PKD1P1 also shares sentences with these, for which no sentence is quoted: breast cancer (4 papers); tumor (3); COVID-19 (1); Hypertension (1); infection (1); triple-negative breast carcinoma (1).